RNU6-213P (RNA, U6 small nuclear 213, pseudogene)
Synonyms: RNU6-1033P
Gene: Small nuclear RNA gene on chromosome 16 (15,877,163 to 15,877,266, reverse strand). Ensembl gene ENSG00000206778.
Homologues: Orthologues: chimpanzee U6 (99% identical), macaque U6 (89% identical), guinea pig U6 (82% identical). Paralogues in human: RNU6-21P (87% identical), RNU6-33P (87% identical), RNU6-40P (87% identical), RNU6-761P (87% identical), RNU6-80P (87% identical), RNU6-1 (86% identical), RNU6-1031P (86% identical), RNU6-144P (86% identical), RNU6-15P (86% identical), RNU6-2 (86% identical), RNU6-20P (86% identical), RNU6-3P (86% identical), and 1287 more.